ELAVL1 (ELAV like RNA binding protein 1)
Diseases named in the same sentence as ELAVL1 in open-access papers (continued):
Sharing a sentence is not in itself a finding about the gene and the disease.
tumor (continued). "Taken together, our experimental data provide compelling evidence that targeted suppression of ELAVL1 impedes tumor growth." (PMID 39390359, 2024). "Other small-molecule inhibitors, such as the microtubule inhibitor MPT0B098 and abemaciclib, were able to inhibit ELAVL1/HuR activity, resulting in reduced tumor growth." (PMID 38689093, 2024). "ELAVL1 promotes the expression of certain tumor-related genes, such as ZMYM1 and DRG1, in an m6A-dependent manner, thereby exerting pro-carcinogenic effects." (PMID 37744335, 2023). "The differential effects and distinct molecular pathways associated with AHR and ELAVL1 modulation highlight their potential as therapeutic targets for PDAC treatment, particularly in overcoming chemoresistance and inhibiting tumour progression." (PMID 37685961, 2023). "LINC00707, which is highly expressed in tumor tissues, has been shown to form a complex with ELAVL1 protein." (PMID 35465324, 2022). "In 47 PCa samples, we found that ELAVL1 was indeed more highly expressed in PCa than in para-tumor tissues." (PMID 35978821, 2022). "Immunohistochemical analyses of 77 paired HCC surgical specimens demonstrated that diffuse ELAVL1 expression was detected more frequently in HCC tissues (61.0%) than in non-tumor tissues (27.3%)." (PMID 35887229, 2022). "Concordant with these findings, our immunohistochemical analyses revealed that 70/77 (90.9%) of tumor samples were positive for ELAVL1." (PMID 35887229, 2022). "Among 47 tumor samples with diffuse expression patterns, 13 cases (16.9%) demonstrated ELAVL1 expression not only in the nuclei but also in the cytoplasm of HCC cells." (PMID 35887229, 2022). "LINC00336 acts as an oncogene that promotes tumor cell proliferation, inhibits ferroptosis, and induces tumor formation in an ELAVL1-dependent manner." (PMID 36105219, 2022). "In animal experiments, overexpressing ELAVL1 in RKO cells results in increased tumor sizes upon injection into nude mice." (PMID 35465324, 2022). "Although 13 tumor tissues exhibited not only nuclear expression but also cytoplasmic expression of ELAVL1, only two cases demonstrated co-expression of ELAVL1 in the non-tumor tissues." (PMID 35887229, 2022). "In TCGA data, ELAVL1 was found to be highly expressed in almost all tumors, indicating that high ELAVL1 expression is closely related to tumor development." (PMID 35978821, 2022). "Accordingly, the cytoplasmic localization of ELAVL1 has been shown to be significantly positively correlated with tumor stage." (PMID 35465324, 2022). "In view of the positive regulation of ELAVL1 in tumor promotion, the research and development of inhibitors is of significance." (PMID 35465324, 2022). "Hypoxia in the tumor microenvironment can similarly induce nucleocytoplasmic shuttling of ELAVL1, which then promotes the expression of the PIM1 serine/threonine kinase, which leads to resistance to oxaliplatin." (PMID 35465324, 2022). "On the other hand, the tumorigenic effects of high expression of ELAVL1 acts as an important contributor to the progression and invasion of many types of tumor through various pathways." (PMID 35465324, 2022). "To further investigate the correlation between miR‐4496 (ELAVL1) and CCAT2 in HCC patients' tumour tissue, we examined miR‐4496 and ELAVL1 expressions by qRT‐PCR and IHC of 61 HCC specimens." (PMID 34409736, 2021). "HuR (ELAVL1) is an RNA-binding protein that plays a positive role in regulating tumor survival and invasion." (PMID 34899345, 2021). "Mechanistically, BCAR4 participates in tumor progression via sponging miR-139-3p to upregulate ELAVL1 in ESCC." (PMID 33602031, 2021). "Another study on melanoma found that the RNA-binding protein ELAVL1 was overexpressed in tumor tissue and significantly correlated with tumor progression and prognosis, promoting tumor formation and inhibiting cancer cell senescence." (PMID 33195699, 2020).
tumor (continued). "Results showed that the levels of AMPK and LKB1 in a large majority of the tumor samples were lower than the normal controls, the levels of ELAVL1 and LPCAT2 in tumor samples were higher than the normal control (p < 0.05)." (PMID 32733803, 2020). "In summary, our study illustrates that LINC00336 functions as an oncogene to facilitate tumor cell proliferation, inhibit ferroptosis, and induce tumor formation in an ELAVL1-dependent manner." (PMID 30787392, 2019). "For instance, HuR (also known as ELAV like RNA binding protein 1) is a mRNA stabilizing protein for which its deregulated nucleus: cytoplasm ratio leads to tumor initiation and progression." (PMID 31097003, 2019). "Our study found that the expression of ELAVL1 was significantly high in tumor samples, while that of other three members (ELAVL2, ELAVL3 and ELAVL4) was significantly low in tumors." (PMID 28035070, 2017). "The RNA-binding protein ELAVL1 is known to regulate tumor cell proliferation and apoptosis, but its role in MDV-induced oncogenesis remains unclear." (PMID 41829051, 2026). "Furthermore, increased cytoplasmic levels of ELAVL1 have been correlated with advanced tumor stage and unfavorable outcome." (PMID 39390359, 2024). "Interestingly, UBA2 mRNA expression was significantly induced and strongly correlated with ELAVL1 in the tumor, in contrast to the paired ST of a cohort of patients with HCC." (PMID 38507413, 2024). "Relative to athymic mice inoculated with NC cells, those inoculated with shELAVL1 cells exhibited a reduced tumor burden, intimating that ELAVL1 may potentiate cisplatin resistance." (PMID 39555714, 2024). "When ELAVL1 is silenced, the programmed death of tumor cells increases and invasion is inhibited." (PMID 35465324, 2022). "ELAVL1 was expressed in the nuclei of hepatocytes at varying frequencies in non-tumor tissues." (PMID 35887229, 2022). "Several studies have found a tumor-promoting effect of ELAVL1 in various tumors." (PMID 35978821, 2022). "ELAVL1 could promote the proliferation of tumor cells by directly binding ER or regulating epidermal growth factor receptor-2 (ERBB2), cyclooxygenase-2 (COX-2) and VEGF-A through a series of signal transduction pathways." (PMID 36261786, 2022). "ELAVL1 has been reported to be involved in tumor occurrence." (PMID 35978821, 2022). "In addition, cumulative studies have found that ELAVL1 is not only related to tumor occurrence and progression but also to radiotherapy resistance and chemotherapy resistance." (PMID 35978821, 2022). "ELAVL1 may rely on m6A to participate in the regulation of RNA metabolism of m6A regulators or interact with m6A regulators to play a tumor-promoting role." (PMID 35978821, 2022). "Finally, the expression of ELAVL1 gene is highly induced in the tumor tissue of a cohort of CCA patients, according to The Cancer Genome Atlas (TCGA) mRNA expression repository." (PMID 35681645, 2022). "Similarly, our study also showed that compared with para-tumor tissue, PCa tumor tissue had stronger ELAVL1 staining and a higher H-score." (PMID 35978821, 2022). "However, we corroborated the tumor-suppressive roles of insertions in Adk and Zbtb20 and in Nipbl, Pdlim5, Ppp1r12a, Tnrc6b, Brd4, Cul3, Ctnna3, Elavl1, Gphn, Nfia, Ptpn12, Taok3, and Rasa1." (PMID 33435458, 2021). "ELAVL1 levels are also downregulated by miR-22, which has a more profound tumor-suppressive effect." (PMID 31440515, 2019). "ELAVL1 levels are downregulated by miR-519, a tumor-suppressive miRNA." (PMID 31440515, 2019). "Finally, we investigated the effect of ELAVL1 on EC tumor growth in vivo." (PMID 40018990, 2025). "In addition, ELAVL1 is highly expressed in PCa and can promote tumor proliferation." (PMID 35978821, 2022).
tumor (continued). "In another mode of regulation for miR-199a, hypoxia-induced expression of ELAVL1 prevents the maturation of pre-miR-199a, thereby promoting enhancement of glycolysis through impacts of miR-199a on hexokinase 2 and pyruvate kinase 2 expression in the tumor microenvironment." (PMID 35465324, 2022). "Therefore, we speculate that ELAVL1 in PCa may be involved in tumor development by regulating the RNA metabolism of m6A regulators." (PMID 35978821, 2022). "In addition to the factors mentioned, it is likely that other SFs identified here as having consistent changes across all tumor types (SNRPB, RNPS1, RBM34, ELAVL1, and RALYL) could contribute to tumor-associated splicing events in the analyzed datasets." (PMID 33621242, 2021). "HuR (ELAVL1), an RNA-binding protein that promotes tumor progression and resistance, has been effectively knocked out using CRISPR/Cas9." (PMID 41301838, 2025). "Mechanistically, circTFRC enhanced the interaction between ELAVL1 and SCD1 mRNA, leading to increased SCD1 stability and expression, which in turn contributed to ferroptosis evasion and tumor advancement." (PMID 40473597, 2025). "BECN1, ELAVL1, and ATG16L1 were highly expressed in tumor tissues, while NCOA4, FTH1, FTL, SNCA, TNF, ATG7, and ZFP36 showed low expression levels." (PMID 39593730, 2024). "Studies have shown that circRNAs can bind to RBPs, such as Quaking (QKI), HuR (ELAVL1), eukaryotic translation initiation factor 4A3 (EIF4A3), and AlkB homolog H5 (ALKBH5), to play important roles in tumor progression." (PMID 37296107, 2023). "The results demonstrated that CBLL1, ELAVL1 and YTHDF1 expressed more in tumor samples than in normal samples of LUAD and LUSC patients, while the expression level of ZC3H13 in tumor samples is lower than in normal samples of LUAD and LUSC patients." (PMID 36261786, 2022). "According to the color and quantity of positivity: ELAVL1 was expressed in stages I–III and was differentially expressed between tumor and normal tissues." (PMID 36324584, 2022). "Except for ZC3H13, the other three genes (CBLL1, ELAVL1 and YTHDF1) were positively correlated with purity state of tumor cell in LUSC." (PMID 36261786, 2022). "It appeared that IGF2BP1/3, ELAVL1, HNRNPA2B1, HNRNPC, KIAA1429, RBM15, LRPPRC, FMR1, YTHDF1/2 are highly expressed in the tumor while FTO, METTL14/16, WTAP, YTHDC1 and ZC3H13 are down-regulated." (PMID 35095993, 2021). "Our data show that seven m6A regulators (CBLL1, ELAVL1, LRPPRC, RBM15B, YTHDF1, YTHDF2, and ZC3H13) are related to tumorigenesis, tumor microenvironment and tumor prognosis." (PMID 33670062, 2021). "The results showed that ELAVL1, YTHDF2, RBM15, HNRNPA2B1, ALKBH5A, and RBM15B expression was significantly upregulated in tumor tissues compared with normal tissues (p < 0.05)." (PMID 34900988, 2021). "In this study, we show that SNHG12 binds to HuR to target ELAVL1 and YWHAZ, both of which are established tumor progression-related genes, and promotes GC cell proliferation via the YWHAZ/AKT/GSK-3β axis." (PMID 34195070, 2021). "For example, ELAVL1 promotes the stability and translation of COX-2 mRNA by binding to its ARE sequences located within the 3′UTR in an advanced tumor stage of CRC tissues." (PMID 31440515, 2019). "miR-22 directly binds to the 3′UTR of ELAVL1 leading to its inhibition, which, in turn, represses CRC proliferation and migration in vitro and decelerates CRC xenografted tumor growth in vivo." (PMID 31440515, 2019). "In summary, we determined the high expression of BAP31, ELAVL1 and SPINK6 in HCC tissues, knockdown of BAP31, ELAVL1 or SPINK6 recovered the cell polarity and inhibited the invasion and migration in HCC cells, and suppressed the tumor formation and lung metastasis in mice models." (PMID 39990675, 2025).
tumor (continued). "Stable over-expression of CMTR1 or ELAVL1 into HGC-27 cells resulted in increase of growth, tumor weight, CD31-positive microvessels, and Ki-67 proliferative index of subcutaneous xenografts formed in nude mice, accompanied by up-regulation of CD44v, which were prevented by knockdown of SNORA37." (PMID 39815331, 2025). "In addition, tumor weight data were as expected: mice receiving BAP31, ELAVL1 or SPINK6 knockdown HCC cells had lighter tumors, while SPINK6 overexpression partially compensated for the decrease of tumor weight caused by depletion of BAP31 or ELAVL1." (PMID 39990675, 2025). "Among the fourteen ferritinophagy-related genes studied, ten exhibited significant differences between tumor and normal samples: NCOA4, FTH1, FTL, SNCA (all p < 0.0001), BECN1 (p = 0.031), ELAVL1 (p = 0.00023), TNF (p = 0.00074), ATG16L1, ATG7, and ZFP36 (all p < 0.0001)." (PMID 39593730, 2024). "This may suggest that ELAVL1 and ZC3H13 have a better anti-tumor immunity, which was in accordance with previous studies." (PMID 36261786, 2022). "The staining strength for ELAVL1 of the nuclei in tumor tissues was stronger than that in adjacent non-tumor tissues in most cases." (PMID 35887229, 2022). "Also, in A2780 cells, glucose deprivation has been shown to enhance ELAVL1-dependent TUBB3 expression at the mRNA and protein levels, resulting in tumor invasion." (PMID 35465324, 2022). "In addition, many RNA-binding proteins, such as ZFP36/TTP, ELAVL1/HuR, and RBM10, can regulate ferroptosis in tumor cells." (PMID 33980834, 2021). "Collectively, data in the present study indicated that ELAVL1 may be downstream gene of miR-139-3p sponging to BCAR4, which are involved in tumor progressions in ESCC." (PMID 33602031, 2021). "In contrast to TTP, genetic alterations of the ELAVL1 gene do not routinely occur in tumor cells or primary tumors." (PMID 23665903, 2013). "Moreover, tumor growth curve showed that BAP31, ELAVL1 or SPINK6 knockdown decreased tumor growth, while SPINK6 overexpression could counteract this improvement." (PMID 39990675, 2025). "Correlation analysis of the alternative splicing events of CD44 with expression levels of CELF1 and ELAVL1 based on RNA-Seq data from TCGA revealed that high expression of CELF1 and/or ELAVL1 is correlated with the inclusion of CD44 variable exons in eight tumor types." (PMID 38106992, 2023). "Of the 77 non-tumor samples, 37 (48.1%) and 21 (27.3%) were classified as partial expression (<50% of nuclei in hepatocytes) and diffuse expression (≥50% of nuclei in hepatocytes) patterns, respectively, but 19 (24.6%) demonstrated no expression of ELAVL1." (PMID 35887229, 2022).
infection (42 papers, 2008 to 2026). The state of being infected such as from the introduction of a foreign agent such as serum, vaccine, antigenic substance or organism. "During primary infection, hub protein such as Elavl1, Btg2, Fkbp5, Hug, Hsp90a.1 are also top in the betweenness ranking." (PMID 25341656, 2014). "We then analyzed the role of ELAVL1 during infection with DNA and RNA viruses." (PMID 39707025, 2025). "Exploring substantial evidence connecting the role of ELAVL1 in HBV replication and the role of ELAVL1 in HCC is needed to be addressed in future studies through the role of ELAVL1 in real infection experiments using HepG2-NTCP cells or primary human hepatocytes." (PMID 35887229, 2022). "Reduced ELAVL1 expression may weaken inflammatory responses against MTB, impairing the host’s ability to effectively counteract infection." (PMID 39622968, 2024). "Exogenous hsa_circ_0000280 did not alter CDKN1A expression after si-ELAVL1 infection." (PMID 36477660, 2022).
intestinal diseases (1 paper, 2018). "Although most of these ARE-associated factors have gained attention as post-transcriptional modifiers in immunopathology, Elavl1/HuR is a well-studied example of clinical relevance to intestinal diseases." (PMID 30532756, 2018).
ELAVL1 also shares sentences with these, for which no sentence is quoted: lung adenocarcinoma (14 papers); osteosarcoma (14); meningioma (10); cardiovascular disease (9); metabolic disease (9); Obesity (9); renal carcinoma (9); Hepatic steatosis (8); myocardial infarction (8); brain tumors (7); kidney disease (7); asthma (6); cardiac hypertrophy (6); lymph node metastasis (6); neurological disorders (6); gallbladder cancer (5); inflammatory bowel disease (5); neurodegenerative disease (5); renal fibrosis (5); steatosis (5); chronic lymphocytic leukemia (4); dyslipidemia (4); Glucose intolerance (4); heart failure (4); Hypertension (4); ischemic stroke (4); malignant glioma (4); renal cell carcinoma (4); Stroke (4); thyroid (4).
A further 195 diseases each share a sentence with ELAVL1 in 4 papers or fewer.